CTLA4 (cytotoxic T-lymphocyte associated protein 4)
Diseases named in the same sentence as CTLA4 in open-access papers (continued):
Sharing a sentence is not in itself a finding about the gene and the disease.
cancer (continued). "Moreover, although a slight rise of sPD-L1 was observed in our experimental setting analyzing cancer patients treated with anti-CTLA-4 and anti-PD-1, these levels were not comparable with the stronger increases observed in anti-PD-L1-treated patients." (PMID 32033266, 2020). "In addition, the occurrence of irAEs predicted a favorable OS in patients with cancer receiving PD-1 inhibitors (HR, 0.51, 95% CI, 0.40–0.64, p < 0.001), but not CTLA-4 inhibitors (HR, 0.89, 95% CI, 0.49–1.61, p = 0.706)." (PMID 32306958, 2020). "However, the relevance of CTLA-4 rs231775 has not been consistently reported in every disease condition and is even less pronounced in cancer than in autoimmune diseases." (PMID 32732985, 2020). "Currently, some of the ICIs including the anti-CTLA-4 agent, ipilimumab, Tremelimumab; anti-PD-1 agents, nivolumab and pembrolizumab; and anti-PDL-1 agent, Atezolizumab, Avelumab, Cemiplimab, Durvalumab, ipilimumab, and atezolizumab have been approved for the treatment of certain types of cancer." (PMID 33333816, 2020). "While high ranking suggests high chance of success if indications are chosen without pre-selecting patients within the cancer type, a low ranking of the cancer type does not suggest all patients of that cancer type should be ineligible for clinical trials of new anti-CTLA-4 antibodies." (PMID 31991588, 2020). "Despite the convincing data from mouse models, there has not been direct evidence indicating that anti-CTLA-4 immunotherapy could efficiently deplete Tregs in human cancers." (PMID 30863404, 2019). "Interestingly, disease-associated TEX in chronic infection were further characterized by co-expression of inhibitory receptors TIGIT and 2B4 (as well as some KLRG1 and CD160) while in cancer, TEX more frequently exhibited higher expression of CTLA-4, Lag-3, and CD39." (PMID 32038613, 2019). "In addition, the ligation of CTLA-4 with the B7 family co-stimulatory molecules of CD80 and CD86 induces IDO1 expression in DCs; therefore, IDO1 is an important immunotherapy target in cancer treatment." (PMID 30658461, 2019). "Therefore, antibodies targeting CTLA-4, CCR4, and/or GITR on Treg cells can deplete Treg cells, reverse T cell dysfunction, and restore T cell antitumor immunity and immune surveillance on cancer cells." (PMID 31379886, 2019). "To evaluate the efficacy of MIR155HG in predicting cancer patient response to checkpoint inhibitor, we used the TIMER database to analyze the relevance of MIR155HG and the currently available blocking molecules with superior therapeutic effects PD‐1, PD‐L1, CTLA4, LAG3, TIM3." (PMID 31568700, 2019). "Due to the redundancy of the multiple checkpoints, EMT may render cancer cells non-responsive to therapies targeting one or few checkpoints (e.g., anti-PD-L1 and anti-CTLA4)." (PMID 31137625, 2019). "CTLA4 had no expression in nearly all the cancer cell lines (#7) and many different cancer types." (PMID 31358815, 2019). "Besides CTLA-4 and PD-1/PD-L1 targeted mAbs, development of mAbs against other checkpoint molecules of T cells, e.g., TIM-3, LAG-3 and TIGIT, and various combinations of ICI mAbs are also underway for the treatment of various cancers." (PMID 31468283, 2019). "Thus, inhibition of these activities may be considered a good therapeutic target; CTLA-4, for example, is found to be highly expressed in HPV-related cancer when compared to HPV-negative samples." (PMID 29854832, 2018). "A major breakthrough in cancer immunotherapy was the discovery that immunomodulation of Tcells’ through immune check-points, such as programmed death 1 and its ligand (PD1-PDL1) and cytotoxic T-lymphocyte antigen 4 (CTLA4), induces immune evasion of cancer cells." (PMID 29520483, 2018). "However, cancer patients with low-expression levels of CTLA-4 (type III ovarian cancer) will be not sensitive to anti-CTLA-4 therapy." (PMID 32793247, 2018).
cancer (continued). "The occurrence of cancer in eight of 17 CTLA-4 patients without any immunosuppression indicates that there may be an intrinsic defect to control especially the herpes viruses, EBV, and CMV in CTLA-4 insufficient individuals." (PMID 30250467, 2018). "Inhibition of the blocking responses to T cell activation using anti-PDCD1, anti-CTLA4, or anti-CD274 antibodies has proven clinically to result in improved responses for a subset of patients with metastatic melanoma, NSCLC, and potentially other forms of cancer." (PMID 28822103, 2018). "Nevertheless, CTLA4 has not been mentioned in the cancer census gene list." (PMID 30443258, 2018). "Thus, the next era of immunotherapy will involve the search for safe combinatory anti-cancer agents which do not interfere with the PD-1/PDL-1 or CTLA-4 immunomodulatory mode of action and do not potentiate related toxicities." (PMID 29237435, 2017). "In the late 1990s, Allison and his group began to study how CTLA-4 inhibits T-cells and if this inhibition could explain why T-cells do not attack cancer cells." (PMID 28050779, 2017). "Because the ligand–receptor interactions of these checkpoints could be blocked by antibodies or recombinant ligands or receptors, several antibodies against CTLA-4 and PD-1 have been approved by the FDA for cancer immunotherapy, and many other antibodies are in development." (PMID 28280600, 2017). "Importantly, the ligands of CTLA-4 B7-1 (CD80) and B7-2 (CD86) are expressed on antigen presenting cells (APC) but not on cancer cells, whereas the ligands of PD-1, PD-L1 and PD-L2, are expressed on APC and on cancer cells." (PMID 27510264, 2016). "Nevertheless, it is likely that anti-CTLA4 therapy plays a dual role by both removing pre-existing T regulatory cells and by blocking CTLA4-mediated suppression of CD4 and CD8 effector T cells; together permitting improved clearance of residual cancer cells following radiation therapy." (PMID 27281029, 2016). "However, single-agent checkpoint inhibitors that alter immune suppressive signals in other human cancer such as CTLA-4, PD-1 and its ligand PD-L1, have failed to demonstrated objective response when given as single agents to PDA patients." (PMID 27191744, 2016). "A meta-analysis showed that CTLA-4 +49A/G polymorphism may be a risk factor for cancer, whereas -318C/T and +6230G/A (CT60) polymorphisms were lack of association with cancer." (PMID 24710335, 2014). "As a homolog of CTLA-4, CD28 may also contribute to the development of cancer." (PMID 23133541, 2012). "TIGIT cancer immunotherapy may be made more effective by combining it with additional “braker” drugs, such as anti-CTLA-4, anti-vascular endothelial growth factor (VEGF), a triple combination of TIGIT+PD-1/PD-L1+CTLA-4 or TIGIT+PD-1/PD-L1+VEGF, or chemotherapy." (PMID 38229100, 2024). "Therefore, immune checkpoint inhibitors (ICIs), including cytotoxic T lymphocyte antigen-4 (CTLA-4), programmed cell death protein 1 (PD-1)/programmed cell death-ligand 1 (PD-L1) axis, indoleamine 2,3-dioxygenase (IDO), etc., are now the frontline of immunotherapy for a variety of cancers." (PMID 36593951, 2023). "Currently, an inhibitor of the T-lymphocyte-associate antigen 4 (CTLA-4) and six inhibitors of the programmed cell death protein pathway (PD-1/PD-L1) have received regulatory approval from US Food and Drug Administration (FDA) for different cancer types, but not in gliomas." (PMID 37165457, 2023). "Importantly, this also suggests that anti-CTLA4 or anti-PD-L1 immunotherapies might be worth exploring in the setting of early disease, where other mechanisms of immune evasion seen in advanced cancers may not have developed yet." (PMID 38136440, 2023). "Similarly, a substantial proportion of cancer patients treated with immune checkpoint inhibitors (ICI) develop immune-related adverse events (irAE), with a reported incidence of ~ 20% of high grade irAE for anti-PD1 treatment and of ~ 60% for the combination of anti-PD1 and anti-CTLA4." (PMID 36997937, 2023).
cancer (continued). "In conclusion, our study shows that ICB with anti-PD1 antibodies in PLWH with cancer had a very limited impact on HIV reservoirs and immunity to HIV which might be explained by an ICP compensatory phenomenon as assessed by the early increase in CTLA-4 and Tim-3 expression." (PMID 35326466, 2022). "In addition, a pan-cancer study highlighted that altered PARP1 was correlated with the high degree of immune cell infiltrations, such as CD8+ T cells, in most cancers, simultaneously, there were higher expression levels of PD-1, LAG3, and CTLA-4 in the PARP1-altered group." (PMID 36818471, 2022). "However, cancer may mimic normal cells by using negative feedback mechanisms, such as the inhibitory receptors, programmed cell death protein 1 (PD-1), and CTLA-4." (PMID 35054524, 2022). "Given the unprecedented predictive values of PD-L1 and CTLA-4 expression in immunotherapy, investigating the diverse regulators on PD-L1 and CTLA-4 expression that could potentially influence immunotherapy efficacy will contribute to the individualized clinical management of cancer patients." (PMID 34088360, 2021). "As anti-CTLA-4 and anti-PD-1/PD-L1 are established therapies that are utilized in the clinic, we hypothesized that the addition of ICB to anti-TGFβ therapy has the potential to induce durable complete responses that are infrequently seen with TGFβ inhibition alone in transplantable cancer models." (PMID 34789823, 2021). "However, only two of them CTLA-4 and PD-1 are primarily and broadly explored and their blockade is used as a therapeutic procedure in the routine treatment of several cancers: among others, in the treatment of advanced melanoma, non-small cell lung cancer, non-Hodgkin’s lymphoma, and kidney cancer." (PMID 33519815, 2020). "Furthermore, cancer cells directly evade immune surveillance and the antitumoral actions of natural killer cells by activating immunosuppressive mechanisms elicited by heterophilic complexes, joining cancer and immune cells, formed by PD-L1/PD1 and CD80/CTLA-4 plasma membrane proteins." (PMID 32555170, 2020). "Up to date the immunotherapeutic effects have been achieved through the antagonistic activity of the anti-CTLA-4 antibodies, i.e., blocking the checkpoint that can prevent autoimmunity and immune responses against cancer, thus making it difficult to achieve cancer immunity without irAEs." (PMID 32781690, 2020). "However, little evidence showed correlations between CTLA-4 and prognosis in cancer patient." (PMID 28211499, 2017). "Thus, there is no doubt that anti-CTLA-4 mAb therapy, as well as in combination with other immune-activating agents, could offer a significant improvement in antitumor immune effect in cancer patients." (PMID 28211499, 2017). "But with the discovery of CTLA-4 as a potent inhibitory immune checkpoint, the notion about cancer immunotherapy was modified and the preferred approach was understood as not to activate the immune system to attack cancer but to remove the coinhibitory signals that block antitumor T cell responses." (PMID 28018338, 2016). "Similarly, human cancers that are not responsive to anti-PD-1 and/or anti-CTLA-4 may require additional immune modulation if patients are to be converted to durable responders." (PMID 27610613, 2016). "Having identified that there are striking changes in the expression levels of the immune and cancer modules in responders versus non-responders, we reasoned that targeting these modules with drugs could potentially increase the response rate to anti-CTLA-4." (PMID 26193793, 2015). "Functionality in response to polyclonal stimuli was not affected by cancer or therapy, although induction of LAG-3 and CTLA-4 was impaired in both Vδ1 and Vδ2 cells." (PMID 41310392, 2026).
cancer (continued). "Similarly, vital immune checkpoint genes such as HAVR2, CD274, CTLA4, ITGB2, ICAM1, CCL5, CXCL10 all exhibited robust correlation with IFI30, and this immunotherapy might, in the future, establish a bond with IFI30, bringing new opportunities for cancer treatment." (PMID 39925804, 2025). "By targeting PD-1 and CTLA-4 checkpoints, ICB non-specifically promotes T cell responses, including those involved in anti-cancer and anti-viral immunity." (PMID 37369658, 2023). "With the role of this ICI in T cell exhaustion in cancer, it will be important to consider this as a mechanism in cardiovascular events in those without LAG-3, like the PD1(-/-) and CTLA-4-negative mice." (PMID 38136253, 2023). "Increased expression of VISTA was observed not only after treatment with anti-PD1 alone but also in combination with CTLA-4, proving the activation of VISTA pathway after these treatments and explaining their non-efficacy in various aggressive cancers." (PMID 37662962, 2023). "KMPlot analysis showed that cancer patients with high MNAI had significantly prolonged PFS after anti-PD-1 (p = 0.00021) and anti-CTLA-4 (p = 0.00071) treatment but not after anti-PD-L1 treatment (p = 0.22)." (PMID 37456231, 2023). "We examined the therapeutic effects of CTLA-4–blocking mAbs, with or without LEM, using 4T1, E0771, or MC38 syngeneic mouse models of cancer." (PMID 35239514, 2022). "CTLA4, PDCD1, and LAG3 were significantly up-regulated in 4–5 cancers, while all of them were not dysregulated in PRAD." (PMID 35741849, 2022). "We did identify a CTLA4+/TIM3+ CD8+ T cell subset, however, no significant changes in its frequency were observed in the presence of PRAME overexpressing cancer cells (data not shown)." (PMID 34612587, 2021). "It is now known that although immunotherapy with antibodies against PD1, CTLA4, or PDL1 demonstrates significant efficacy, a significant number of cancer patients do not respond to immune-checkpoint therapy." (PMID 34516769, 2021). "Since the tracer signal in the murine cancer model was not ideal, a subsequent PET imaging study was performed using ipilimumab, a FDA-approved anti-human CTLA-4 IgG1, in humanized mice." (PMID 33391977, 2021). "Despite therapies targeting CTLA4, PD1, and PDL1 have shown success in many cancers, although not all patients respond well to these therapies." (PMID 33796453, 2021). "It occurs with any type of currently available ICI, anti-CTLA4, anti-PD1 or anti PD-L1, at any time of treatment and regardless of the type of cancer." (PMID 31857638, 2019). "Expression of CTLA-4 on human NK cells remains elusive, and the effect on NK cells of drugs targeting the CTLA-4 pathway in cancer patients has not been studied." (PMID 29023417, 2017). "Tremelimumab, a monoclonal antibody, binds to cytotoxic T lymphocyte protein 4 (CTLA4) to stimulate human immune system and has been undergoing human trials for the treatment of various cancers but has not attained approval for any." (PMID 28903454, 2017). "This review is limited in scope to ICIs (anti-CTLA-4, anti-PD-1, anti-PD-L1, anti-LAG-3) and does not detail other immunotherapeutic modalities (oncolytic viruses, cytokine therapies, adoptive cell transfer, cancer vaccines)." (PMID 42292486, 2026). "Notably, high Nrf2 expression was also correlated with worse survival outcomes in cancer patients undergoing immune checkpoint inhibitor therapies, including anti‐PD1 and anti‐CTLA‐4 treatments, irrespective of cancer types (middle)." (PMID 40755294, 2025). "In addition, our pan-cancer analysis revealed a negative correlation between p62 and PD-1 in four cancers (BRCA, LIHC, PRAD, THCA), and with CTLA-4 in eight cancers (KIRC, ESCA, READ, COAD, PAAD, BRCA, PRAD, THCA)." (PMID 41291343, 2025).
cancer (continued). "When the immune homeostasis between the positive (TCR/MHC) and negative (CTLA-4/CD80, PD-1/PDL-1) signals for T cell activation is disrupted, cancer cells can evade the host’s immune response and escape from the attack of immune cells, thereby growing and proliferating uncontrollably." (PMID 41357573, 2025). "Recently, although immunotherapies represented by anti-CTLA-4 antibodies and PD1/PD-L1 antibodies have made their debut in anti-cancer clinical practice, the lack of universally accepted paradigm for the immune escape of cancer is one of the reasons limiting the effect of immunotherapies." (PMID 38976030, 2024). "Furthermore, our study discovered that PD-L1, but not CTLA4, is expressed on the cancer cell surface and anti-PD-L1 scFv from CF33-hNIS-antiPDL1-infected cells significantly blocked PD-L1 on cancer cells." (PMID 37762490, 2023). "Blockage of CTLA-4 by an anti-CTLA-4 antibody inhibits CD28-dependent T-cell activation, and the regulation of these negative co-stimulatory molecules has been used in radical cancer therapy." (PMID 36180526, 2022). "Although there are no approved anti-CTLA-4-Treg inhibitors for CaCx to date, the presence of Tregs in HPV-induced cancers including CaCx, suggests the use of monoclonal antibodies to act as check point inhibitors in CaCx, but this remains to be an area of research." (PMID 33924844, 2021). "Thus, we investigated the potential influence of NTF3 expression on cancer immunotherapy and found a positive correlation between NTF3 expression and immune checkpoints, including PD-L1, TIGIT, and TIM-3, but not CTLA4." (PMID 34938753, 2021). "In our opinion, antibodies or small molecules that inhibit CTLA-4, but do not alter CTLA-4 levels in Treg cells, could be innovative and ultimately more effective in eradicating cancer cells." (PMID 33809974, 2021). "Similarly, ligands for CTLA4 (CD86 and CD80) were almost never expressed in cancer cells." (PMID 31427603, 2019). "Therefore, CTLA4 and PD1 can be used as targets of immunotherapy for the 5 cancer types but might not be appropriate for LGG." (PMID 31842801, 2019). "Interestingly, analyzing sera from additional cancer patients treated with anti-CTLA-4, anti-PD-1, or anti-PD-L1 mAbs in monotherapy, we showed that a significant increase of sPD-L1 was detected only in patients treated with anti-PD-L1 but not with anti-CTLA-4 or anti-PD-1 mAbs." (PMID 32033266, 2020). "Thus, although NK cells might be important players that contribute to the anti-tumor activity of IC inhibitors (ICIs) like antibodies against CTLA-4, LAG3, and the PD1/PD-L1 axes in cancer patients, this should not overestimate the function of some T cell-ICs in healthy NK cells." (PMID 31998304, 2019). "Therefore, the targeting of CTLA-4 and PD-1 negative immune checkpoints-based immune suppression pathway along with some other important regulatory checkpoints such as Siglec factors and CD47-SIRPα may contribute to the upgrade of immune responses against cancer cells." (PMID 36109471, 2023).